AGPAT5 (1-acylglycerol-3-phosphate O-acyltransferase 5)
Description:
Converts 1-acyl-sn-glycerol-3-phosphate (lysophosphatidic acid or LPA) into 1,2-diacyl-sn-glycerol-3-phosphate (phosphatidic acid or PA) by incorporating an acyl moiety at the sn-2 position of the glycerol backbone. Acts on LPA containing saturated or unsaturated fatty acids C15:0-C20:4 at the sn-1 position using C18:1-CoA as the acyl donor. Also acts on lysophosphatidylethanolamine using oleoyl-CoA, but not arachidonoyl-CoA, and lysophosphatidylinositol using arachidonoyl-CoA, but not oleoyl-CoA. Activity toward lysophosphatidylglycerol not detectable.
Synonyms: LPAAT-epsilon; FLJ11210; LPAAT-e; LPLAT5; 1AGPAT5; LPAATE
Tractability: Antibody: UniProt predicts a signal peptide or a membrane-spanning region. PROTAC: ubiquitination databases record sites on it; its protein half-life has been measured.
Target class: Enzyme; Transferase
Gene: Protein-coding gene on chromosome 8 (6,708,341 to 6,761,503, forward strand). Ensembl gene ENSG00000155189.
Subcellular location: Endoplasmic reticulum membrane; Nucleus envelope; Mitochondrion
Subcellular location (Human Protein Atlas): Mitochondria
Pathways (Reactome):
Metabolism: Synthesis of PA
Gene Ontology:
Molecular function: 1-acylglycerol-3-phosphate O-acyltransferase activity; protein binding; 1-acylglycerophosphocholine O-acyltransferase activity; 1-acylglycerophosphoethanolamine O-acyltransferase activity; 1-acylglycerophosphoserine O-acyltransferase activity; acyltransferase activity
Biological process: phosphatidic acid biosynthetic process; phosphatidylinositol acyl-chain remodeling; phospholipid biosynthetic process; CDP-diacylglycerol biosynthetic process; glycerophospholipid metabolic process
Cellular component: endoplasmic reticulum membrane; mitochondrion; nuclear envelope; endoplasmic reticulum; mitochondrial outer membrane
Genetic constraint (gnomAD): Loss-of-function variants: 38 observed, 35.82 expected, observed/expected ratio (o/e) 1.06, 90% interval 0.82 to 1.39. The synonymous counts are far from expectation, so gnomAD's model fits this gene poorly and the ratio says little. Missense variants: 613 observed, 423.11 expected, observed/expected ratio (o/e) 1.45, 90% interval 1.36 to 1.55. Synonymous variants: 255 observed, 158.1 expected, observed/expected ratio (o/e) 1.61, 90% interval 1.46 to 1.79.
Homologues: Orthologues: chimpanzee AGPAT5 (99% identical), macaque AGPAT5 (99% identical), dog AGPAT5 (88% identical), pig AGPAT5 (88% identical), mouse Agpat5 (82% identical), rat Agpat5 (82% identical), guinea pig AGPAT5 (71% identical), zebrafish agpat5 (69% identical), Caenorhabditis elegans acl-11 (34% identical). Paralogues in human: LCLAT1 (25% identical), AGPAT4 (22% identical), AGPAT3 (21% identical), LPGAT1 (20% identical).
Diseases named in the same sentence as AGPAT5 in open-access papers:
AGPAT5 is named in the same sentence as 13 diseases in open-access papers, as found by Europe PMC text mining. Sharing a sentence is not in itself a finding about the gene and the disease. The quoted sentences say what the papers report.
breast carcinoma (3 papers, 2014 to 2023). "It has also been reported that miR-26, which is downregulated by estrogen in breast cancer cell lines, can directly target AGPAT5 via its 3′UTR." (PMID 36845084, 2023). "The most upregulated proteins by SBP1 induction included DKK1 that inhibits WNT pathway, DHCR7 that controls cholesterol and Vitamin D synthesis, ANXA4 that inhibits NFkB pathway and IL-8, and AGPAT5 that inhibits breast cancer cell proliferation." (PMID 25974208, 2015).
Hypoglycemia (3 papers, 2022 to 2024). A decreased concentration of glucose in the blood. "Another study in mice identified Agpat5 within a genome-wide significant QTL associated with hypoglycemia-induced glucagon secretion." (PMID 39608054, 2024). "Two studies claimed that Irak4 (Interleukin-1 receptor associated kinase-4) controls hypoglycemia-induced glucagon secretion by modulating hypothalamic Il-1β signaling, and Agpat5 activation in AgRP (agouti-related protein) neurons leads to hypoglycemia-induced glucagon secretion." (PMID 37764697, 2023). "Another study demonstrated that expression of Agpat5 in agouti-related peptide neurons in the hypothalamus contributes to hypoglycemia-induced glucagon secretion." (PMID 39608054, 2024). "We demonstrated that Agpat5 inactivation in AgRP neurons led to reduced hypoglycemia-induced glucagon secretion." (PMID 36180454, 2022). "In summary, our study identified Agpat5 expressed in AgRP neurons as required for hypoglycemia-sensing by a population of AgRP neurons and for efficient triggering of glucagon secretion." (PMID 36180454, 2022). "In a genetic screen of recombinant inbred BXD mice we previously identified Agpat5 as a candidate regulator of hypoglycemia-induced glucagon secretion." (PMID 36180454, 2022). "Agpat5 appeared as the most likely candidate regulator of hypoglycemia-induced glucagon secretion of the chromosome 8 QTL5." (PMID 36180454, 2022). "The role of Agpat5 is, thus, to ensure that AgRP neurons respond faithfully to developing hypoglycemia." (PMID 36180454, 2022). "Here, using genetic mouse models, we demonstrate that Agpat5 expressed in agouti-related peptide neurons is required for their activation by hypoglycemia, for hypoglycemia-induced vagal nerve activity, and glucagon secretion." (PMID 36180454, 2022). "Our physiological studies show that inactivation of Agpat5 in AgRP neurons suppresses their activation by hypoglycemia, impairs hypoglycemia-induced vagal nerve activity, and reduces glucagon secretion." (PMID 36180454, 2022). "Thus, inactivation of Agpat5 led to a reduction in the number of AgRP neurons that can be activated by hypoglycemia as detected by c-Fos staining, patch clamp analysis, and in vivo intracellular Ca2+ recordings." (PMID 36180454, 2022). "As our own screen was based on insulin-induced hypoglycemia Agpat5 could, in principle, mediate its effect on glucagon secretion by controlling insulin sensitivity and hypoglycemia development and/or on hypoglycemia sensing." (PMID 36180454, 2022). "Here, we investigated the role of Agpat5 as a regulator of hypoglycemia-induced glucagon secretion." (PMID 36180454, 2022). "The identical rates of hypoglycemia development after insulin injection in control and mutated mice also indicated that insulin sensitivity was not modified by Agpat5 inactivation in AgRP neurons." (PMID 36180454, 2022). "Thus, Agpat5 in AgRP neurons was required for normal hypoglycemia-induced glucagon secretion." (PMID 36180454, 2022). "Thus, in conditions of hypoglycemia, the role of Agpat5 may be to prevent fatty acyl-CoAs from entering the mitochondria for FAO ensuring that reduced ATP production reflects the decrease in blood glucose concentrations." (PMID 36180454, 2022). "That circulating FFAs indeed blunt glucagon secretion through an Agpat5-dependent mechanism was confirmed by showing that the impaired glucagon response to hypoglycemia of AgRPAgpat5KO mice could be largely reverted when circulating free fatty acids were lowered by nicotinic acid treatment." (PMID 36180454, 2022). "In mice with inactivation of both Agpat5 and Cpt1a, hypoglycemia did not induce a significant reduction in glucagon secretion as compared to Agpat5flox/flox;Cpt1aflox/flox mice." (PMID 36180454, 2022).
Hypoglycemia (continued). "An intriguing observation is that inactivation of Agpat5 reduces the number of AgRP neurons activated by hypoglycemia without changing the electrophysiological properties of the remaining GI neurons and without reducing the total number of AgRP neurons." (PMID 36180454, 2022). "Thus, Agpat5 in AgRP neurons plays a role in hypoglycemia sensing but not in whole body insulin sensitivity." (PMID 36180454, 2022).
hepatocellular carcinoma (2 papers, 2023 to 2025). A malignant tumor that arises from hepatocytes. "First, we explored the expression of AGPAT5, LCLAT1, and LPCAT1 in common hepatocellular carcinoma cell lines by data mining in the CCLE database." (PMID 36845084, 2023). "Similarly, LCLAT1 expression was recently found to be upregulated in hepatocellular carcinoma (HCC), compared to normal liver tissue, and along with AGPAT5 and LPCAT1, was identified as a highly sensitive biomarker that correlated with worse prognosis and overall survival." (PMID 41473749, 2025).
dyslipidemia (1 paper, 2024). "Overall, genetic studies across multiple species strongly support a role for Agpat5 in metabolic diseases, including hyperinsulinemia, glucose intolerance, metabolic dysfunction-associated steatotic liver disease (MASLD), and dyslipidemia." (PMID 39608054, 2024). "Genetic evidence strongly supports a role for Agpat5 in contributing to hyperinsulinemia, glucose intolerance, hepatic steatosis, and dyslipidemia." (PMID 39608054, 2024).
glioblastoma (1 paper, 2023). The most malignant astrocytic tumor (WHO grade IV). "In glioblastoma, there is increased expression of AGPAT5, AGPAT9/LPCAT1, and AGPAT11/LPCAT2 compared to healthy brain tissue." (PMID 37046844, 2023). "In particular, AGPAT5, AGPAT6/GPAT4, AGPAT8/ALCAT1/LCLAT1, AGPAT9/LPCAT1, and AGPAT11/LPCAT2 show higher expression in glioblastoma tumors than in healthy tissue." (PMID 37046844, 2023).
Glucose intolerance (1 paper, 2024). Glucose intolerance (GI) can be defined as dysglycemia that comprises both prediabetes and diabetes. "Our study provides strong evidence that in the liver Agpat5 contributes to hyperinsulinemia and glucose intolerance when consuming liquid sucrose by altering specific glycerophospholipids." (PMID 39608054, 2024). "Liver-specific deletion of Agpat5 improved plasma insulin levels and glucose intolerance only in mice fed a chow diet supplemented with liquid sucrose." (PMID 39608054, 2024). "We show that liver-specific expression of Agpat5 contributes to hyperinsulinemia and glucose intolerance only in mice consuming a chow diet supplemented with liquid sucrose drinking water." (PMID 39608054, 2024). "One study showed that targeting Agpat5 in mice with antisense oligonucleotides improves hyperinsulinemia and glucose intolerance." (PMID 39608054, 2024). "However, when mice are supplemented with liquid sucrose—a dietary intervention that increases de novo lipogenesis (DNL), liver-specific Agpat5 deletion significantly improves hyperinsulinemia and glucose intolerance." (PMID 39608054, 2024). "Liver-specific deletion of Agpat5 did not affect body weight or fat mass and yet still had improved plasma insulin levels and glucose intolerance when fed a chow diet supplemented with liquid sucrose." (PMID 39608054, 2024). "Overall, these data show that liver-specific deletion of Agpat5 significantly improves the development of hyperinsulinemia and glucose intolerance in mice on chow diet with liquid sucrose without changing body weight or fat mass." (PMID 39608054, 2024).
Hepatic steatosis (1 paper, 2024). Steatosis is a term used to denote lipid accumulation within hepatocytes. "Here, we conducted a series of metabolic studies under four distinct dietary conditions to assess the impact of liver-specific Agpat5 deletion on plasma insulin levels, glucose tolerance, plasma cholesterol levels, and hepatic steatosis." (PMID 39608054, 2024). "To investigate the effect of liver-specific Agpat5 deletion, we also measured hepatic steatosis and plasma lipid levels among the four dietary interventions." (PMID 39608054, 2024). "Liver-specific deletion of Agpat5 did not affect plasma insulin levels, glucose tolerance, plasma cholesterol levels, or hepatic steatosis in mice fed a chow diet, high-fat diet, or Western diet." (PMID 39608054, 2024). "Our data show that liver-specific deletion of Agpat5 does not impact plasma insulin levels, glucose tolerance, hepatic steatosis, or plasma lipid levels under multiple dietary conditions." (PMID 39608054, 2024).
Hyperinsulinemia (1 paper, 2024). An increased concentration of insulin in the blood. "In mice and humans, there is strong genetic data supporting a role for Agpat5 in contributing to hyperinsulinemia, glucose metabolism, MASLD, and plasma lipid metabolism." (PMID 39608054, 2024). "Overall, our findings indicate a liver-specific role of Agpat5 in contributing to hyperinsulinemia and glucose tolerance in the absence of body weight changes when consuming liquid sucrose." (PMID 39608054, 2024).
cancer (6 papers, 2015 to 2024). A tumor composed of atypical neoplastic, often pleomorphic cells that invade other tissues. "Contrary to some counterparts in the AGPAT family implicated in cancer, AGPAT5 diverges in its impact." (PMID 38893234, 2024). "Its expression diminishes in colorectal cancer, and higher levels are associated with a more favorable prognosis for patients with this cancer, suggesting an anticancer characteristic of AGPAT5." (PMID 38893234, 2024). "We explored the expression levels of AGPAT5, LCLAT1, and LPCAT1, the three core genes of the prognostic model, in normal and pan-cancer tissues based on XENA-TCGA-GTEx datasets." (PMID 36845084, 2023). "Common CNLs negatively influencing DFS and cancer-specific OS harboured the feline orthologous of multiple HBC-related genes reported as commonly deleted including FOXP1, FBXO25, CSMD1, AGPAT5, PCM1, PTPRG, and PDGFRL15,19,27,28,41–43." (PMID 31969654, 2020). "This chromosomic region harbours the CSMD1, AGPAT5, TUSC3, DLC1, CLDN23, and MFHAS1 cancer-related genes." (PMID 30185896, 2018).
tumor (3 papers, 2020 to 2026). "In addition, we verified common tumor-associated protein markers and found that after the knockdown of AGPAT5, their VEGF levels were significantly reduced, along with a significant trend of Vimentin reduction." (PMID 36845084, 2023). "Furthermore, we confirmed the ability of major members of this gene family to participate in tumor cell proliferation, migration, and invasion by silencing AGPAT5, LCLAT1, and LPCAT1, respectively, in HepG2 cell lines." (PMID 36845084, 2023). "The results of tissue samples showed that AGPAT5, LCLAT1, and LPCAT1 were significantly upregulated in HCC tumor tissues than in adjacent normal tissues." (PMID 36845084, 2023).
metabolic disease (1 paper, 2024). A congenital disorder (due to inherited enzyme abnormality) or acquired (due to failure of a metabolically important organ) disorder resulting from an abnormal metabolic process. "Among the AGPAT enzymes, Agpat5 (1-Acylglycerol-3-Phosphate O-Acyltransferase 5) is unique in its cellular localization, substrate specificity, and genetic data supporting its role in metabolic disease." (PMID 39608054, 2024).
AGPAT5 also shares sentences with these, for which no sentence is quoted: metabolic dysfunction-associated steatotic liver disease (1 paper); retinoblastoma (1).